EGFR (epidermal growth factor receptor)
Diseases named in the same sentence as EGFR in open-access papers (continued):
Sharing a sentence is not in itself a finding about the gene and the disease.
tumor (continued). "Our work demonstrated that SMAD4 can promote the aggressive tumor behavior and induce NE phenotype and EGFR-TKI and pemetrexed resistance independently of RB1 status for the first time." (PMID 38233864, 2024). "The most common mutant of EGFR in GBM is EGFRvIII, expressed in 31% of patients, and overexpression or amplification of EGFR is a feature of aggressive primary GBM and associated with tumour infiltration." (PMID 39009914, 2024). "Amivantamab in 15 NSCLC patients with EGFR ex20ins demonstrated promising clinical anti-tumor activity." (PMID 38774882, 2024). "EGFR was expressed in the BMC tumour area in 100% (46/46) of samples; 45.7% (21/46) of samples had low expression, and 54.3% (25/46) of samples had high expression." (PMID 39073672, 2024). "These BiTEs bound to CD3 on T cells and EGFR simultaneously, allowing the CAR-T cells to target tumor cells expressing EGFRvIII, EGFR, or both." (PMID 38473776, 2024). "The patient's tumor developed resistance to BRAF/MEK/EGFR inhibition with MET amplification, but remained sensitive to FOLFIRI, suggesting MET amplification did not induce resistance to irinotecan." (PMID 39626159, 2024). "The CMVs exhibit enhanced targeting capability via excellent ligand-mediated affinity to epidermal growth factor receptor (EGFR)or HER2 on the tumor surface." (PMID 39698409, 2024). "Statistical analysis also revealed that Stage III disease was frequently seen with EGFR wild-type tumours (p < 0.008)." (PMID 38539465, 2024). "REG4 activates CREB1 by interacting with its receptor, EGFR, in tumour cells, resulting in increased SRGN expression." (PMID 38862740, 2024). "In summary, through a generalizable pipeline for screening TAAs by single-cell transcriptomic and IHC analysis, MUC1 was selected as a candidate target to combine with EGFR, as to increase the tumor specificity over normal cells." (PMID 39664199, 2024). "EGFR blocking reduce tumor cell proliferation, survival, angiogenesis and migration by inhibiting the activity of MAPK and PI3K signaling." (PMID 38370365, 2024). "It appeared that tumor sites with positive staining of EGFR were comparable between the vehicle and pembrolizumab groups, while EGFR+ sites were less abundant in amivantamab and combination treated groups." (PMID 38916448, 2024). "They compared the amplification of EGFR with various clinical factors, including patient age, tumor volume, and overall survival." (PMID 38674026, 2024). "Most normal tissues show low levels of EREG expression, but the levels are elevated in different cancer types and promote tumor progression by activating EGFR signaling." (PMID 38334792, 2024). "We observed that high expression of RTKs including EGFR and ErbB2 sensitized cancers to ferroptosis-inducing tumor treatment." (PMID 39604370, 2024). "Despite these interesting results, the sample size analyzed in this study was too small, and further studies are needed to clarify the relationship between neoadjuvant chemotherapy and anti-EGFR-based tumor detection." (PMID 38883274, 2024). "From our findings, we demonstrated that activation of this signaling axis can be highly heterogeneous even within the same tumor, and this heterogeneity defines, as expected, response to anti-EGFR treatment." (PMID 39061010, 2024).
tumor (continued). "Since EGFR-mediated signaling potentiates glycolytic metabolism, this phenomenon can induce a self-sustaining deleterious loop, favoring tumor growth." (PMID 39329717, 2024). "In this regard, a study showed that recombinant anti-EGFR CAR-T cells exhibit specific cytolytic activity against EGFR-positive tumor cells and can release cytokines, displaying potential in fighting NSCLC." (PMID 39015563, 2024). "Multi-omics analysis were performed to dissect the tumor immune microenvironment features at baseline and after resistance to third-generation EGFR-TKIs treatment." (PMID 39638994, 2024). "In lung adenocarcinoma, EGFR mutations are prevalent and are often associated with increased levels of inflammatory cytokines like IL-6 and TNF-α, which contribute to tumor progression." (PMID 39990858, 2024). "Increased co-expression of EGFR and HER2 is associated with advanced tumor stages, aggressive phenotypes, distant metastases, and shorter overall survival." (PMID 38793045, 2024). "On the other hand, Cetuximab is amonoclonal antibody directed against the epidermal growth factor receptor(EGFR); the EGFR gene amplification and protein overexpression in glioblastomaimplies most aggressive to the tumor." (PMID 39285908, 2024). "11eg is selective against mutant EGFRs and exhibits a tumor growth inhibition of 70.6% in xenograft models with minimal toxicity, making it a promising candidate for treating NSCLC with EGFR C797S mutations." (PMID 39337496, 2024). "LiTE-containing mouse serum collected at 4 hours and 4 days after LiTERNA-LNP i.v. administration mediated EGFR-specific cytotoxicity of CT26EGFR tumor cells ex vivo, indicating full functionality of the antibody produced in vivo (dashed blue line)." (PMID 39835115, 2024). "This suggested that a large proportion of the tumor actively upregulated the expression of EGFR and MET in one of multifaceted responses to pembrolizumab." (PMID 38916448, 2024). "It has been suggested that TEADs are mediators of the EGFR/RAS/RAF/MAPK pathway and play a crucial role in tumor progression and drug resistance in NSCLC with EGFR, KRAS, or BRAF mutation." (PMID 38499647, 2024). "The studies evaluated show that its heterogeneity varies with the mutation type (EGFR, ALK), tumor stage, distribution of histological subtypes, and frequency of co-alterations." (PMID 39001401, 2024). "Amivantamab (EGFR-MET bispecific antibody) with lazertinib has shown anti-tumor activity with ORR 36% and PFS 4.9 m in patients of disease progression upon EGFR-TKI." (PMID 38402169, 2024). "Fluorescently labeled cetuximab can be utilized for targeted FMI of OSCC to evaluate the targeted recognition of anti-EGFR fluorescently labeled antibodies in and around the tumor after systemic administration." (PMID 39183296, 2024). "ADCT, consisting of the tumor-targeted, antibody-mediated transfer of membrane fragments from tumor cells to effector cells, significantly contributes to the removal of both EGFR and MET from the cancer cell surface." (PMID 38892318, 2024). "The QD/lipid micelles (QDMs) were prepared using a simple self-assembly procedure and then conjugated with anti-epidermal growth factor receptor (EGFR) antibodies for tumor targeting." (PMID 38892434, 2024). "Other key driver gene amplifications, specifically MET, EGFR and FGFR2, in circulating tumor DNA were associated with numerically lower ORR." (PMID 38745009, 2024). "Cetuximab is a monoclonal antibody that binds to the epidermal growth factor receptor (EGFR) on tumor cells and blocks the receptor-dependent transduction pathway." (PMID 39559603, 2024). "In HNSCC PDX tumor, a subcluster with high expression of EGFR simultaneously had elevated level of MET." (PMID 38916448, 2024). "Despite high tumor response rates with first‐line EGFR‐TKIs, approximately 60% of patients encounter secondary EGFR T790M mutations at the time of acquired resistance." (PMID 38832214, 2024).
tumor (continued). "This BiKE effectively mediated NK cell activation and later displayed enhanced EGFR-specific tumor cell lysis compared to FDA approved EGFR-targeted antibody cetuximab." (PMID 39911822, 2024). "When they withdrew doxycycline or treated with first-generation EGFR TKI erlotinib, they observed tumor regression, indicating that these mutations are indeed required for tumor maintenance." (PMID 39796653, 2024). "Categories and genes related to cell stemness, EGFR signaling, apoptosis, DNA repair, and interaction between tumor cells and the immune system were also present in our analysis." (PMID 39513883, 2024). "Different types of integration of EML4 with ALK or other genes, the presence of a secondary mutation in ALK, and activation of alternative signaling pathways such as EGFR, are the mechanisms by which tumor cells become resistant." (PMID 38234663, 2024). "Several UCHL1 substrates have been described in tumour cells including Epidermal Growth Factor Receptor (EGFR), Transforming Growth Factor β (TGF-β), SMAD2, and importantly for our current study, Hypoxia Inducible Factor 1 α (HIF1α)." (PMID 38808772, 2024). "Of note, spatial distribution analysis showed that EGFR overexpression was localized in the infiltrating tumor edge, providing further evidence of the relevance of the EGFR for the invasion capacity of GBM cells." (PMID 38727302, 2024). "Exposure to arsenic has been associated with the phosphorylation of the epidermal growth factor receptor (EGFR), which then triggers cellular proliferation, tumour invasion, and angiogenesis." (PMID 39846533, 2024). "EGFR is highly or aberrantly expressed in a variety of cancers, stimulates proliferation, angiogenesis, and metastasis, and protects tumor cells from apoptosis." (PMID 38375031, 2024). "Ultimately, EGFR-TKIs impede tumor growth, proliferation, and differentiation, inducing apoptosis in tumor cells." (PMID 39211774, 2024). "Activation of the EGFR pathway leads to increased PD-L1 expression in tumor cells, facilitating T-cell apoptosis and immune evasion." (PMID 39015563, 2024). "Third, we investigated the effect of EREG on tumor development by using only several HCC lines with different levels of EGFR expression." (PMID 38673992, 2024). "Cutaneous inflammatory rash is the most common adverse effect of EGFR inhibitors used for tumor therapy." (PMID 38059627, 2024). "Targeted therapies against EGFR, whose levels significantly increase in tumor cells but are also found in healthy host tissues, show limited effectiveness." (PMID 39407936, 2024). "We clearly distinguished tumor tissues from normal tissues by immunohistochemical staining for EGFR and PD-L1." (PMID 39183296, 2024). "EGFR siRNA LPX + UTMC inhibited tumor growth and suppressed EGFR expression in vivo, suggesting that this platform holds promise for non-invasive, image-guided targeted delivery of therapeutic siRNA for cancer treatment." (PMID 38577322, 2024). "Previous studies reported the role of ROS in EGFR activation and the correlation between ROS and EGFR in tumor progression and drug resistance." (PMID 39001381, 2024). "For instance, the anti-tumor effect of αPD-1-IL-15-R, which targets PD-1, is more potent than that of αEGFR-IL-15-R, which targets EGFR." (PMID 39664443, 2024). "Epidermal growth factor (EGFR) strongly drives tumor proliferation, metastasis, invasion and migration through various signal pathways." (PMID 38967523, 2024). "High levels of EGFR and Ki67 expression are linked with more aggressive tumors, while low p16 expression and COX-2 levels suggest varying prognoses based on tumor localization and age." (PMID 39459468, 2024). "The application of TKIs, especially those targeting EGFR and ALK mutations, modulates the tumor immune microenvironment in patients with NSCLC, contributing to the development of resistance." (PMID 39766230, 2024). "EVs conjugated with EGFR antibody-modified functional PEG can target tumor cells overexpressing EGFR receptors." (PMID 39802949, 2024).
tumor (continued). "The activation of the epidermal growth factor receptor (EGFR) signaling pathway promotes the secretion of insulin-like growth factor-1 (IGF-1), which in turn induces tumor-associated macrophage polarization." (PMID 39619695, 2024). "In glioma, EVs containing EGFR proteins can offer a specific marker for the tumor and the precise detection of the tumor." (PMID 39685907, 2024). "EGFR is a protein expressed on the surface of tumor cells, which can promote the growth and survival of tumor cells." (PMID 38974045, 2024). "This study demonstrated a mechanism linking EGFR signalling with Fyn and Src activation to promote tumour progression and invasion and provided a rationale for combined anti-EGFR and anti-SFK targeted therapies." (PMID 39697541, 2024). "Zhang's study also indicated that anti‐PD‐1 inhibitors toripalimab plus chemotherapy showed a promising anti‐tumor efficacy with a tolerable safety profile for NSCLC patients after progression on EGFR TKI therapies (ORR 54.8%, mPFS 7.6 months)." (PMID 39406371, 2024). "MSK-LX29 tumor was derived from the patient with EGFR mutant NSCLC who developed resistance after 3 months of erlotinib treatment with an acquired MET amplification and had the highest TWIST1 expression." (PMID 38485737, 2024). "In summary, this study not only highlights the importance of targeting EGFR trafficking in medical oncology but also reveals a novel mechanism involving tumor suppressor genes." (PMID 38338651, 2024). "Mutations in EGFR can activate downstream signaling pathways, such as PI3K/Akt and MAPK, enhancing the metastatic potential of tumor cells to colonize distant organs, including the breast." (PMID 39193383, 2024). "Genetic depletion or pharmacological inhibition of BCAT1 impaired the growth of resistant cells and partially re-sensitized tumor cells to EGFR TKIs." (PMID 39143065, 2024). "The epidermal growth factor receptor (EGFR) signaling pathway plays an important role in tissue development and tumor development and has been previously shown to regulate the expression of Runx2 and Osterix." (PMID 38956429, 2024). "The response of EGFRm+ NSCLC tumor to the third-generation EGFR TKI osimertinib was evaluated in established PDX tumors." (PMID 39041204, 2024). "Meanwhile, CALM1, which together with CALM2 encodes calmodulin (CALM), has been reported to have synergistic effects with EGFR in promoting tumor metastasis, resulting in a poor prognosis." (PMID 38462627, 2024). "Around 57.4% of individuals with primary GBM exhibit EGFR gene amplification, resulting in elevated levels of EGFR protein and promoting tumor proliferation and growth." (PMID 38686058, 2024). "Following a detailed, retrospective analysis of the trials, the benefit of afatinib in this patient group in terms of tumor response and PFS was published, leading to the registration of afatinib for the treatment of NSCLs with rare EGFR mutations." (PMID 38605928, 2024). "Meanwhile, up-regulated HIF-1α bound to the promoter of HPRT1 and transcriptionally activates HPRT1 expression, enhancing purine metabolism to maintain rapid tumor cell proliferation in EGFR-mutant LUAD." (PMID 39343971, 2024). "These cells were designed to recognize both this tumor-specific antigen, as well as the wild-type EGFR protein, through the secretion of a T cell-engaging antibody molecule (TEAM)." (PMID 39134804, 2024). "Patients with advanced NSCLC can achieve excellent tumor control after a period of EGFR-TKI treatment." (PMID 38204337, 2024). "(i) Anti-EGFR-targeted Gd10B6 NPs delivered high amounts of 10B (158 μg/g tumor) and 157Gd (56.8 μg/g tumor) to head and neck tumors in mice, enabling effective combined GdBNCT with long survival times." (PMID 39055339, 2024). "Excessive expression of EGFR enhances these pathways, boosting tumor cell proliferation and metastasis." (PMID 39415846, 2024).
tumor (continued). "To further investigate the prognostic implications of CNVs in the migratory SC-f tumor subtype, we tested the EGFR (7p11.2) gains with a migratory tumor signature in HR+/HER2-BC using the TCGA-BRCA." (PMID 38892065, 2024). "Opioids directly stimulate tumor growth and progression via mu-opioid receptors and costimulation of the epidermal growth factor receptor (EGFR)." (PMID 38248102, 2024). "Several studies suggest the tumor suppressor role of PTPRK, further supported by its association with TGF-β and EGFR signaling pathways." (PMID 38999976, 2024). "It is reported that the overexpression of c-Met occurs in about 20–25% of patients with NSCLC and persistently stimulates PIK3CA, MAPK, and STAT pathways to bypass EGFR, thereby inducing the malignant progression of the tumor." (PMID 39468027, 2024). "These secreted BiTEs helped CAR T cells kill EGFR expressing tumor cells by recruiting bystander T cells as well as re-directing CAR T cells." (PMID 39835140, 2024). "This indicates that ER cells have developed a robust mechanism to bypass EGFR inhibition and promote tumor growth, which is crucial for understanding resistance mechanisms." (PMID 39897079, 2024). "One of the most promising of these is the affibody ZEGFR:1907, which exhibits a high affinity to the EGFR (Kd of 5.4 nM) and has already been used in 18F- and 64Cu-labeled form for the imaging of EGFR-expressing human tumor cells in xenografted mice." (PMID 39458921, 2024). "In one study, NSCLC patients with ALK fusion showed EGFR gene activation in 44% of tumor samples after developing resistance to ALK TKI crizotinib." (PMID 39582541, 2024). "Conversely, YTHDF2 also functions as a tumour suppressor by hastening the degradation of EGFR transcripts, which in turn curtails HCC growth." (PMID 38239038, 2024). "If ROS levels in tumor cells are high, the probe will fluoresce, indicating that the tumor cells are sensitive to EGFR-TKI and that the patient is suitable for EGFR-TKI therapy." (PMID 39451714, 2024). "Our intent was to establish tumors that heterogeneously expressed HER2 and EGFR on different tumor cell populations." (PMID 38711454, 2024). "In contrast, spotty ECM texture is linked to higher overall frequency of tumor cells and mildly related to presence of cells with co-amplified PDGFRA/EGFR." (PMID 38805346, 2024). "Unfortunately, post-BRAFi lesions were not sufficiently represented in the patient cohort that we had available to allow us to reliably assess the prevalence of EGFR expression on tumor tissues following gain of BRAFi-resistance." (PMID 38510242, 2024). "Lower expression mRNA levels of MALAT1 were associated with pathologic stage and lymph node metastasis and tumor T status in all LADC or EGFR wild-type." (PMID 38517388, 2024). "Targeted therapy, represented by selective EGFR-TKIs, has great importance because it not only effectively inhibits tumor growth but also has fewer side effects than chemotherapy." (PMID 38429828, 2024). "Despite these advances, patients with EGFR-mutant metastatic NSCLC inevitably have tumor recurrence and ultimately succumb to metastatic disease." (PMID 39001412, 2024). "Upregulation of EGFR leads to activation of EGFR signaling and promotes tumor progression through EGFR downstream pathways, including PI3K/Akt/mTOR and RAS/MEK/ERK pathways." (PMID 39036344, 2024). "Cases with concomitant classic EGFR mut+/ex20ins+ had a high tumor content (mean 49.4%), 90% of them were poorly differentiated (grade 3), and more than half had tumor necrosis (57.5%)." (PMID 38687753, 2024). "Our findings strongly suggest that standard chemotherapy and targeted therapy inhibiting BRAF/MEK and EGFR impose quite different selection pressures on the tumor cells." (PMID 39626159, 2024). "Epidermal growth factor receptor (EGFR) is abnormally amplified in tumour cases and can be used as one of the targets for cancer therapy." (PMID 38212810, 2024).